TNF (tumor necrosis factor)
Diseases named in the same sentence as TNF in open-access papers (continued):
Sharing a sentence is not in itself a finding about the gene and the disease.
esophagitis (8 papers, 2010 to 2023). An acute or chronic inflammatory disease affecting the esophageal wall. "In the esophageal mucosa of esophagitis rats, we observed a significant increase in the secretion of COX-2 and TNF-α with increasing chemical damage by acid in the esophageal mucosa." (PMID 34681549, 2021). "Proinflammatory cytokines, IL-1ß, IL-6 and TNF-α are key players in signaling pathways such as NF-κB activation and mitogen activated protein kinase (MAPK) cascade initiation and appear to play important roles in esophageal diseases including RE." (PMID 32408627, 2020). "Intriguingly, previous work by our group has shown that conditioned media from OAC and BO explants, but not normal or oesophagitis, was able to reduce IFN-γ and TNF-α production in CD8 T cells, suggesting that this immunosuppression may arise early in OAC development." (PMID 31354725, 2019).
Fulminant hepatic failure (8 papers, 2009 to 2022). Hepatic failure refers to the inability of the liver to perform its normal synthetic and metabolic functions, which can result in coagulopathy and alteration in the mental status of a previously healthy individual. "Reductions in levels of the tight junction protein, occludin, in intestinal epithelial cells may be caused by the production of TNF-α in mice with fulminant hepatic failure." (PMID 19772664, 2009). "Capillary mixture can reduce the expression of TNF-α, promote the expression of hepatocyte growth factor, and inhibit the apoptosis of hepatocytes in model rats with fulminant hepatic failure." (PMID 31939733, 2020). "TNF-alpha is known to have a significant role in many forms of liver damage, including ischemia, reperfusion, and fulminant hepatic failure." (PMID 26697061, 2015). "EVs secreted from MSCs alleviate immune responses by reducing the expression levels of inflammatory cytokines such as interleukin (IL)-1β, IL-6, and tumor necrosis factor (TNF)-α, which improved liver function and reduced mortality in fulminant hepatic failure mice." (PMID 34707093, 2021).
hantavirus infection (8 papers, 2008 to 2021). "Secretion of THBS1 by endothelial cells can be modulated by proinflammatory cytokines such as TNFα and IL-1, two cytokines that are commonly observed in association with hantavirus infection." (PMID 27486439, 2016). "For hantavirus infections, several patient-specific characteristics such as specific alleles for HLA and TNF-α that are associated with the clinical courses have been identified." (PMID 24090247, 2013). "Tumor necrosis factor-α (TNF-α) is a pro-inflammatory cytokine associated with hantavirus infections in vivo." (PMID 18822184, 2008). "Strong associations of high TGF-β1 with low IL-8, IL-10 and TNF-α serum levels during acute hantavirus infection support this hypothesis." (PMID 22085404, 2011). "The effects of hantavirus infection and TNFα treatment on THBS1 transcription were analyzed using TaqMan." (PMID 27486439, 2016). "It has been established, however, that immune cells stimulated during hantavirus infection release tumor necrosis factor alpha (TNF-α), a strong inducer of adhesion molecules in EC." (PMID 25859243, 2015). "Our data suggest that hantavirus infection activates c-Jun; therefore, it is possible that TNFα may synergizes hantavirus-triggered activation of transcription factors including those involved in THBS1 accumulation." (PMID 27486439, 2016). "Significantly elevated serum levels of IL-2, IL-6, IL-8, TGF-β1 and TNF-α were also observed when the late phase of acute disease was compared with healthy controls, demonstrating a profound and prolonged pro-inflammatory response to hantavirus infection." (PMID 22085404, 2011). "Regarding the upregulation of proinflammatory cytokines, IL-6, tumor necrosis factor-α (TNF-α), and interferon γ (IFN-γ), all capable of activating the endothelium, have been reported to be elevated in hantavirus infections." (PMID 34452419, 2021). "The early phase of acute hantavirus infection (average 6 days after onset of symptoms) was characterized by significant elevation of cytokine expression of IL-2, IL-6, IL-8, TGF-β1 and TNF-α versus healthy controls." (PMID 22085404, 2011). "Cytokine expression of IL-2, IL-5, IL-6, IL-8, IL-10, IFN-γ, TNF-α and TGF-β1 was analysed by ELISA during the early and late phase of acute hantavirus infection (average 6 and 12 days after onset of symptoms, respectively)." (PMID 22085404, 2011). "One of the most investigated cytokine in acute hantavirus infection of both syndromes HFRS and HPS is TNF-α which was almost uniquely found overexpressed in acute hantavirus infection." (PMID 22085404, 2011). "Acute hantavirus infection was characterized by significantly elevated levels of IL-2, IL-6, IL-8, TGF-β1 and TNF-α in both early and late phase compared to healthy controls." (PMID 22085404, 2011). "IL-8, IL-10, IFN-γ, TNF-α and TGF-β1 in early versus late phase of acute hantavirus infection (average 6 and 12 days after onset of symptoms, respectively)." (PMID 22085404, 2011). "However, we as well as others have shown that hantavirus infection does not activate TNFα or IL-1 expression in endothelial cells." (PMID 27486439, 2016).
HELLP syndrome (8 papers, 2012 to 2025). A life-threatening condition that can potentially complicate pregnancy. "Some study results showed that the serum level of TNF-α in women with HELLP syndrome and model rats was elevated." (PMID 29321548, 2018). "Our experimental results show the AT1-AA titer and positive rate were significantly higher in HELLP group, and AT1-AA titer were positively correlated with the level of TNF-α and ET-1 in plasma and the grade of HELLP syndrome." (PMID 29321548, 2018). "Molvarec observed no significant relation between the TNF-alpha G-308 A polymorphism and HELLP syndrome." (PMID 38057745, 2023). "Genes involved in innate immunity, such as Toll-like receptor 4 (TLR4), oligomerization domain 2 (NOD2), and tumor necrosis factor (TNF)-alpha, among others, have been found to be associated with early-onset PE, HELLP syndrome, and severe FGR complicated by PE." (PMID 36313546, 2022). "Indeed, liver of HELLP syndrome women display marked neutrophil infiltration and stain strongly with TNF-α and neutrophil elastase antibody." (PMID 24851923, 2014). "Similar to what is reported in women with HELLP syndrome, animals with HELLP have evidence of increased inflammatory cytokines tumor necrosis factor-alpha (TNF-α), interleukin-17 (IL-17), and cytokine releasing CD4+ and CD8+ T cells." (PMID 30563221, 2018). "Thus, extra-high levels of TNF-α could directly and indirectly harm endothelial liver cells and exacerbates the inflammatory response in this tissue, which, in turn, could contribute to enzyme elevation in HELLP syndrome." (PMID 24851923, 2014). "Damage to vascular endothelial cells produced by antiangiogenic factors, exposure to TNFα, and high levels of active VWF seen in HELLP syndrome may interact and result in thrombotic microangiopathy." (PMID 35208649, 2022).
hemarthrosis (8 papers, 2019 to 2024). Bleeding into the joints. "TNF expression increased in the soft tissue of mice joints after injury and in the synovial fluid of patients suffering from hemarthrosis caused by an ACL injury." (PMID 38856919, 2024). "In addition, the activation of osteoclasts and the resulting osteopenia in the trabecular bone adjacent to the hemarthrosis were prevented in TNF-deficient mice." (PMID 38856919, 2024). "We measured TNFα in synovial lavage from hemophilia mice subjected to hemarthrosis induction and synovial fluid from patients with hemophilic arthropathy (n = 5)." (PMID 31892201, 2019). "IL-1β, IL-6, and MCP1 are involved in inflammation and progression of hemarthrosis in HA mouse models, while in vitro studies utilizing human cartilage cultures have indicated that IL-1β blockade is more effective than TNFα blockade in reducing damage following exposure to blood." (PMID 32595650, 2020). "In patients with haemarthrosis there is a correlation between the haemoglobin concentration in the joint and the level of TNF-α expression in the joint, which could explain the relation between the severity of bleeding and the loss of trabecular bone observed in this study." (PMID 32290832, 2020). "Indeed, when activated by erythrocyte phagocytosis, monocytes and macrophages were reported to produce IL‐1β and TNF‐α in the joint after hemarthrosis, which could explain the control of FLS expression by a negative feedback pathway of IL‐1α but this hypothesis needs to be confirmed." (PMID 33159500, 2020). "In this report, co-administration of dexamethasone either with the 5-day course after each hemarthrosis or a regime resembling the anti-TNFα starting from day 7 resulted in no additional protection compared to FIX-only treatment." (PMID 31892201, 2019). "Both p < 0.01 compared with no anti-TNFα treatment controls) following hemarthrosis comparison to treatment without anti-TNFα." (PMID 31892201, 2019).
hepatosplenic T-cell lymphoma (8 papers, 2013 to 2025). An extranodal, mature T-cell non-Hodgkin lymphoma that originates from cytotoxic T-cells, usually of gamma/delta T-cell type. "Another important aspect to consider is that Hepatosplenic T-cell lymphoma (HSTCL), though rare, is a potential risk associated with the use of tumor necrosis factor inhibitors (TNFis) in treating IBD." (PMID 39768465, 2024). "Hepatosplenic T-cell lymphoma (HSTCL), a rare but aggressive complication, occurs almost exclusively in males under 35 treated with thiopurines—either alone (1 per 10,000 patient-years) or in combination with anti-TNF agents (3 per 10,000 patient-years)—for more than two years." (PMID 41228267, 2025).
Hepatosplenomegaly (8 papers, 2009 to 2025). Simultaneous enlargement of the liver and spleen. "In children with active VL, lower frequencies of circulating MAIT cells with increased levels of CD69 expression and higher proportions of TNF-producing cells were significantly associated with hepatosplenomegaly." (PMID 36189274, 2022). "Instead, childhood hepatosplenomegaly is associated with high levels of TNF and IFNγ in peripheral blood mononuclear cell cultures, and SEA-stimulated whole blood cultures predominantly produced TNFα and the regulatory cytokines IL-6 and TGFβ." (PMID 21912707, 2011). "Adults without ultrasound-detectable periportal fibrosis have reduced rates of hepatosplenomegaly compared to children and have been shown to release only low levels of TNF-α in response to both SEA and SWA stimulation." (PMID 24357629, 2014). "Circulating levels of the classical markers of an inflammatory response, TNFα and IFNγ, may not have been significantly associated with hepatosplenomegaly as they have short-range activity within the tissues of the liver and spleen." (PMID 19149774, 2009). "In contrast, cells from children chronically infected with S. mansoni who present with hepatosplenomegaly in the absence of periportal fibrosis produce high levels of the type 1 proinflammatory cytokine tumor necrosis factor alpha (TNF-α) in response to SEA stimulation." (PMID 24357629, 2014).
hookworm infection (8 papers, 2008 to 2023). "Similarly, to determine the association of pro-inflammatory cytokines with hookworm infection, we measured plasma levels of TNF-α, IFN-γ, IL-12, and IL-17." (PMID 23056659, 2012). "In unstimulated PBMC cultures from negative, nonendemic individuals lower concentrations of inflammatory IL-1β, IL-6, and TNF-α were detected when compared with participants with hookworm infection." (PMID 21772981, 2011). "While Th2 responses to hookworm antigens are well described, a study conducted in Brazil found elevated spontaneous cellular secretion of tumor necrosis factor alpha, a pro-inflammatory cytokine, and interleukin (IL)-10 in individuals with patent hookworm infections." (PMID 18523547, 2008). "Exogenous TFF2 was associated with suppressed TNF-α and IFN-γ production by stimulated human PMBCs, suggesting that elevated TFF2 in the context of hookworm infection could reduce these pro-inflammatory cytokine levels through direct or indirect mechanisms in vivo." (PMID 34662329, 2021). "In CCs, Ascaris lumbricoides or Schistosoma mansoni infections were associated with an impaired Th1-type response (IFN-gamma, IL-6 and TNF-alpha) in PBMCs mainly with SEB stimulations, whereas in TB patients only hookworm infection showed a similar pattern." (PMID 35976976, 2022).
Hyperbilirubinemia (8 papers, 2012 to 2025). An increased amount of bilirubin in the blood. "Increases in interleukin (IL)-6 and tumor necrosis factor-α, which are observed in the early stages of severe burns, have been reportedly associated with hyperbilirubinemia and organ dysfunction." (PMID 39895101, 2025). "The results of this study suggested that PGC-CDs could inhibit levels of IL-6 and TNF-α in the treatment of hyperbilirubinemia and its associated liver damage, thereby reducing the mortality of hyperbilirubinemia." (PMID 36985691, 2023). "To investigate the effect of PGC-CDs on inflammatory factors of liver damage induced by hyperbilirubinemia, we tested the content of IL-6 and TNF-α." (PMID 36985691, 2023). "Serum tumor necrosis factor-alpha and eosinophilic count increased after treatment of neonatal hyperbilirubinemia by PT, which indicates an allergic response to PT in neonates." (PMID 35725569, 2022). "The hyperbilirubinaemia may be due to excessive erythrocyte fragility, leading to haemolysis, with the reduced clearing of haemoglobin breakdown products, or altered bilirubin metabolism due to high TNF-α levels, leading to reduced bilirubin transport into and out of liver cells." (PMID 37766254, 2023). "As an effective inflammatory mediator of TNF-α or endotoxin (LPS), HMGB1 may progressively exacerbate the inflammation and damage of the bile duct, intrahepatic cholestasis, and hyperbilirubinemia during the early stages of ACLF." (PMID 25187820, 2014). "Absence of hyperbilirubinaemia and the inability of neutrophils to migrate into liver tissue in the septic PI3Kγ−/− mice were seen, notwithstanding higher levels of inflammatory cytokines (TNF-α and IL-6) and the chemoattractant MCP-1." (PMID 23152722, 2012).
hyperphosphatemia (8 papers, 2014 to 2026). Abnormally high level of phosphate in the blood. "CKD is represented by states of low-grade chronic inflammation characterized by increased systemic levels of inflammatory markers such as TNF-α and ILs in addition to other complications such as hyperphosphatemia." (PMID 38470493, 2024). "Other regulatory factors include bone morphogenetic proteins, receptor activator of nuclear factor-kB ligand, tumor necrosis factor-alpha, fetuin-A, oxidative stress, hyperphosphatemia, and vitamin D." (PMID 24587279, 2014). "TNF-alpha induces vascular calcification by promoting ALP and the Wnt-β-catenin signaling pathway like hyperphosphatemia." (PMID 32192106, 2020).
Hypocalcemia (8 papers, 2013 to 2025). An abnormally decreased calcium concentration in the blood. "A time-lag between IL-1- and TNF-α-stimulated Ca2+-entry into cells throughout the body from the circulation and IL-1-stimulated Ca2+-release from the bone was suggested to cause the observed LPS-induced hypocalcaemia." (PMID 24993127, 2014). "It has been suggested that hypocalcaemia could be the result of an increased in IL-1 and TNF-α production, although the underlying mechanisms are unclear." (PMID 24993127, 2014). "It should be noted that when SLE patients get hypocalcemia, the level of plasma TNF-α increased significantly." (PMID 35757710, 2022). "The result suggests that the hypocalcemia will make the immune status of SLE patients tend to the Th1 immune environment, which is characterized by the increase of CD8+ T cell numbers and TNF-α levels in peripheral blood." (PMID 35757710, 2022). "Hypocalcemia accompanied by the increase of CD8+ T cells and TNF-α levels in the peripheral blood of SLE patients may represent an enhanced cellular immunity." (PMID 35757710, 2022). "Although we observed differences in OPG/sRANKL ratio between the two groups (higher OPG/sRANKL ratio in breast-fed), but it was not statically meaningful.Known inducers of bone resorption and hypocalcaemia, such as IL1 and TNFα, act indirectly through the production of RANKL." (PMID 24693367, 2013). "Importantly, serum TNF-α, SAA, haptoglobin, and lactate were already increased at −8 and −4 weeks prior to parturition, suggesting that systemic inflammation may precede and contribute to the development of hypocalcemia." (PMID 40284849, 2025).
iron overload (8 papers, 2005 to 2024). "In SAH patients with iron-overload, pathways linked to TNF-α maturation and ROS detoxification were augmented." (PMID 29980709, 2018). "Since ADAM17 expression is associated with ectodomain shedding of TNF-α and sCD1637, our results suggest that the increase in sCD163 and TNF-α is associated with iron-overload and activation of ADAM17 in SAH patients." (PMID 29980709, 2018). "In an independent case series, however, a positive relationship of TNF-α promoter polymorphisms with iron overload severity or its complications was not confirmed." (PMID 16042809, 2005). "CUR and antioxidant NAC treatment decreased the level of IL-6, TNF-α, and TRACP-5b, and enhanced the level of OCN in serum of iron-overload mice." (PMID 31949885, 2019). "Livers of patients with iron-overload, showed significantly increased levels of CD163 and ADAM17, correlating with the increase in sCD163 and TNF-α levels." (PMID 29980709, 2018). "To confirm whether the elevated iron content in the hippocampus induced the release of TNF-α and in turn downregulated the expression of BDNF, we established a hippocampal iron overload mouse model by injecting FAC into the hippocampus of 6-week-old C57BL/6 mice." (PMID 38195497, 2024).
Jaundice (8 papers, 2014 to 2024). Yellow pigmentation of the skin due to bilirubin, which in turn is the result of increased bilirubin concentration in the bloodstream. "Our results showed the involvement of Nf-Kβ and TNF-α similar to that observed in a transgenic mouse model for Jaundice." (PMID 30106954, 2018). "This is not without precedent, since GUDCA was demonstrated to inhibit the production of TNF-α and IL-1β in astroglial cells by preventing the maturation of these cytokines and their consequent release in an experimental model of jaundice, thus preventing astroglial reactivity." (PMID 31024256, 2019). "So it can be speculated that YCSND can treat jaundice by inhibiting the expression of TNF signaling pathway." (PMID 30671125, 2018).
mantle cell lymphoma (8 papers, 2012 to 2025). Mantle cell lymphoma is a rare form of malignant non-Hodgkin lymphoma affecting B lymphocytes in the lymph nodes in a region called the ``mantle zone''. "Variations in the interleukin-10 and tumor necrosis factor genes plus a family history of hematologic malignancies have all been proposed as a potential risk factors for developing mantle cell lymphoma." (PMID 40843808, 2025). "This may be ADAM10: ADAM10 has shown TNF-α sheddase activity in ADAM17-deficient murine fibroblasts and has been implicated in TNF-α production in mantle cell lymphoma." (PMID 22792380, 2012). "Curcumin can inhibit the expression of both TNF-α mRNA and TNF-α protein in mantle cell lymphoma cell lines." (PMID 25665066, 2015). "Upregulation of TNF-α in combination with inhibition of NF-κB activation can increase apoptosis in mantle cell lymphoma cells, presenting a route by which MCL tumors can be targeted." (PMID 29907126, 2018).